PON1 (paraoxonase 1)
Diseases named in the same sentence as PON1 in open-access papers (continued):
Sharing a sentence is not in itself a finding about the gene and the disease.
atherosclerosis (continued). "In addition to profound alterations in lipoproteins, reduced serum PON1 activity has been clearly established in the past decade and could contribute to accelerated development of atherosclerosis in ESRD and in HD." (PMID 22523692, 2012). "Therefore, PON1 is closely linked to the control of oxidative stress and inflammation, mainly at the circulation level, where its association with HDL particles is related to the prevention of atherosclerosis." (PMID 22824324, 2012). "Therefore, pharmacological modulation of PON1 activity or PON1 gene expression could constitute a useful approach for preventing atherosclerosis." (PMID 22548179, 2012). "However, because of theprotective role of PON1 in the development of atherosclerosis, serumPON1 activity could be used as a bio-marker to monitor the cardiovascularhealth among lead workers." (PMID 16882531, 2006). "PON1 inhibits the oxidation of HDL and LDL, offering protection against atherosclerosis, a common MeS-related complication." (PMID 40564199, 2025). "Search strings included combinations of “PON”, “paraoxonase”, “PON1”, “PON2”, and “PON3” together with terms such as “animal models”, “cancer”, “Atherosclerosis”, and “MASLD”." (PMID 41303537, 2025). "Paraoxonase 1, an enzyme carried by HDL components, prevents the oxidative alteration of low-density lipoprotein (LDL), hence obstructing a crucial step in atherosclerosis formation." (PMID 40276550, 2025). "The focus is on oxLDL, log(TG/HDL-C), PON1, and ARE, which are pivotal in the pathogenesis and progression of atherosclerosis." (PMID 39459504, 2024). "Elevated oxLDL and log(TG/HDL-C) levels contribute to oxidative stress and plaque formation, while PON1 and ARE have antioxidant properties that protect against atherosclerosis." (PMID 39459504, 2024). "PON1 cysteine-284 interacts with oxidized LDL to reduce the accumulation of oxidized LDL in the sub-endothelial layer and prevent atherosclerosis progression." (PMID 39408985, 2024). "Paraoxonase-1 (PON-1) is a calcium-dependent enzyme esterase that binds to HDL-c and has antioxidant and anti-atherosclerosis roles." (PMID 39133724, 2024). "The antioxidant activity of PON1 and ARE helps mitigate oxidative stress, a major factor in the initiation and progression of atherosclerosis." (PMID 39459504, 2024). "The PON1 gene is activated by PPAR-γ, which increases synthesis and release of PON1enzyme from the liver, reducing atherosclerosis." (PMID 37958765, 2023). "PON-1 is classified as an accessory protein of high-density lipoprotein (HDL) and modulates the capacity of HDL to protect against the atherosclerosis process through antioxidant and anti-inflammatory activities." (PMID 35308142, 2022). "There is a body of evidence proving that PON1 protects LDL and HDL and cell membranes from oxidative modification and inhibits the progression of atherosclerosis." (PMID 35889799, 2022). "PON1, 2, and 3 have been identified and they are involved in a plethora of diseases, such as PON3 in the process of atherosclerosis." (PMID 36551332, 2022). "Paraoxonase 1 (PON1) protects against lipid oxidation and has an antioxidant and anti-inflammatory role in atherosclerosis." (PMID 35203642, 2022). "PON1 hydrolyses oxidized lipids in LDL, retards atherosclerosis, and predicts the development of cardiovascular disease." (PMID 35889799, 2022). "The most important physiological role of PON-1 is the ability to hydrolyse oxidized LDL (ox-LDL) and thereby delay the onset of atherosclerosis." (PMID 35308142, 2022). "PON1−/− mice show increased aortic O2•− and leukocyte adhesion; conversely, ApoE−/−/PON1+/+ mice show reduced atherosclerosis." (PMID 35883899, 2022).
atherosclerosis (continued). "Additionally, the fact that the conditioned medium of Caco-2 cells overexpressing ApoAI or PON1 is able to protect EC against inflammatory stress is very important, being well known that EC dysfunction is an important step in the inception and progress of atherosclerosis and many other pathologies." (PMID 34944413, 2021). "Association of MPO with HDL has previously been shown to reduce the PON1 activity of HDL and to correlate with increased atherosclerosis." (PMID 34331945, 2021). "In future studies, we will need to investigate the molecular mechanisms, whereby APOA4, LCAT, PON1, and PON3 protect against atherosclerosis in CKD and if improving their levels in HDL will reverse CKD atherosclerosis in model systems." (PMID 34634315, 2021). "We have previously reported that ApoAI, PON1, and ABCA1 levels in the small intestine are inversely correlated with the severity of atherosclerosis." (PMID 34944413, 2021). "Therefore, FGF19 may promote atherosclerosis by inhibiting the protective effect of PON-1." (PMID 32528406, 2020). "These six genes are involved in the development of atherosclerosis, including CRP, endothelin receptor type A (EDNRA), PON 1, fibrinogen alpha chain (FGA), fibrinogen beta chain (FGB), and fibrinogen gamma chain (FGG)." (PMID 32214403, 2020). "Three proteins, including PON1, APOA1, and GPD2, involved in atherosclerosis, cardiovascular disease, and lipid metabolism, were selected for validation via western blotting." (PMID 32566106, 2020). "Although all the properties of paraoxonase 1 are not fully understood, it is known that this enzyme, by affecting the transformation of high-density lipoproteins, may have a protective function against the development of atherosclerosis, which is a consequence of obesity." (PMID 31737129, 2019). "PON1 is a most important enzyme bound to antioxidant and antiatherogenic HDL, responsible for many of HDL's benefits; correlations between PON1, HDL, and atherosclerosis have been well established, both in vivo and in vitro." (PMID 30151068, 2018). "PON1 inhibits the oxidation of HDL and low density lipoprotein (LDL), and is involved in the pathogenesis of a variety of diseases including atherosclerosis." (PMID 30044465, 2018). "Increased PON1 and APOA1 in SO/SOAE pre-treated animals suggests enhanced functionality of HDL as well as protection against oxidative stress-induced atherosclerosis." (PMID 30115989, 2018). "PON1 prevents LDL oxidation and foam-cell formation, thereby inhibiting atherosclerosis development." (PMID 29215336, 2017). "Taking into consideration these studies, in the present study we examined the dose-dependent effects of caffeine on liver PON1, PON3 and ApoA1 protein levels, and we evaluated a possible relationship between caffeine and atherosclerosis." (PMID 29215336, 2017). "Moreover, several studies have shown that lower PON1 paraoxonase activity is associated with atherosclerotic complications, indicating that it is important to determine the phenotype, not just the genotype, when studying atherosclerosis." (PMID 26241956, 2015). "By preventing oxidative stress, PON1 contributes to protecting LDL from oxidative modifications, reducing foam cell formation, and inhibiting atherosclerosis." (PMID 25276769, 2014). "HDL from PON1 ‘knockout’ mice have an increased capacity to oxidize LDL and are more prone to develop atherosclerosis than their wild-type siblings as a consequence of increased oxidative stress." (PMID 25551104, 2014). "In addition, subjects with the LL genotype may have had higher PON1 activity in our study groups, and thus, patients with RVO, who had a lower frequency of the LL genotype, may be more susceptible to LDL oxidation and atherosclerosis in the retinal arteries." (PMID 23441121, 2013). "Human serum paraoxonase-1 (PON1) prevents oxidation of low density lipoprotein cholesterol (LDL-C) and hydrolyzes the oxidized form, therefore preventing the development of atherosclerosis." (PMID 21629682, 2011).
atherosclerosis (continued). "Decreased PON1 activity and mild elevation in hs-CRP have drawn considerable interest, in relation to the development of atherosclerosis that exemplifies a low-grade chronic inflammatory process." (PMID 20459625, 2010). "A number of enzymes participate in processes that protect arteries from atherosclerosis, including P450-enzymes belonging to different cytochrome (CYP) classes, CCTα, sirtuin 1(SIRT1) and paraoxonase-1 (PON1)." (PMID 20604930, 2010). "PON1 is thought to attenuate the oxidationof low-density lipoprotein (LDL) and therefore protect against thedevelopment of atherosclerosis, although the exact mechanisms and substratesfor PON1 are unclear." (PMID 16882531, 2006). "PON1 playsan important role in protection against this diseaseby removing LDL peroxides, whose accumulation is a critical step in thedevelopment of atherosclerosis." (PMID 16882531, 2006). "Similarly, those with diabetes exhibit lower PON1 and HDL-C levels and higher TG levels, correlating with increased oxidized LDL (ox-LDL), atherosclerosis, CVD, and insulin resistance." (PMID 40511456, 2025). "Given the oxidative stress hypothesis of atherosclerosis and HDL’s antioxidant role, research has focused on paraoxonase 1 (PON1), a key enzyme responsible for HDL’s antioxidant properties." (PMID 40564199, 2025). "The enzyme PON1 is supposed, in various studies, to be one of the most important markers, along with HDL cholesterol, to limit LDL cholesterol oxidation, preventing first atherosclerosis and second stroke." (PMID 38474211, 2024). "Abundance of PON1 was decreased in CKD5 in comparison to CVD2, however in both groups with advanced atherosclerosis, the level of PON1 was downregulated in comparison to HVs and patients with initial atherosclerosis." (PMID 38389898, 2024). "However, the specific effects of vigorous-intensity bodybuilding on atherosclerosis biomarkers such as the TG to HDL-C ratio [log(TG/HDL-C)], oxLDL levels, and PON1 and ARE activities remain underexplored, necessitating further research." (PMID 39459504, 2024). "Recent studies reveal that the decrease in serum PON1 activity observed in non-dialyzed and dialyzed CKD patients as well as in renal transplant (RT) patients is linked to an increased vulnerability to atherosclerosis." (PMID 38982880, 2024). "In contrast, the nature of PON1 targets in atherosclerosis and other human diseases is not fully understood." (PMID 39594433, 2024). "In a large prospective cohort of patients with atherosclerosis undergoing coronary angiography, those with the lowest PON-1 activity had a 3.4 times greater hazard of major cardiovascular events compared to those with the highest PON-1 activity." (PMID 35313365, 2023). "Increased serum HDL levels could be related to the antioxidant properties of hesperidin, which increase PON1, and in previous studies, the relationship between paraoxonase activity with HDL‐c and their role in atherosclerosis has been confirmed." (PMID 37970430, 2023). "PON1 is the most studied enzyme in the PON family and its role in cardiovascular disease (CVD), diabetes mellitus (DM), atherosclerosis, obesity, non-alcoholic fatty liver disease (NAFLD), and inflammatory diseases such as chronic liver inflammation has been reported." (PMID 35883764, 2022). "Several mechanisms by which PON1 can delay and reverse atherosclerosis progression were detected in mice overexpressing PON1 and mice lacking PON1, as well as in vitro studies on lipoproteins or macrophage cell lines." (PMID 35889799, 2022). "These recognized atherosclerosis-fighting enzymes include SOD, GPx, GR, CAT, and PON-1." (PMID 36422550, 2022). "Experiments with PON1-knockout mice have indicated that the absence of PON1 leads to an increase in endothelial adhesion molecules and oxidative stress, confirming this enzyme’s role in preventing the onset of atherosclerosis." (PMID 36290781, 2022). "PON1 is an antioxidant that reduces LDL oxidation and prevent atherosclerosis." (PMID 34680168, 2021).
atherosclerosis (continued). "Given their protective functions against atherosclerosis and their yet unidentified roles in kidney disease, APOA4, LCAT, PON1, and PON3 may represent therapeutic targets for CVD in CKD patients." (PMID 34634315, 2021). "It forms hetero-oligomers that stabilize paraoxonase 1 (PON1), a plasma enzyme known for its antiatherogenic properties; HPBP could thus be indirectly involved in protection against atherosclerosis." (PMID 33670786, 2021). "Importantly, in vivo scavenging of reactive dicarbonyls improved PON1 activity and HDL cholesterol efflux function, supporting this as a potential therapeutic strategy for reducing atherosclerosis." (PMID 32629758, 2020). "The main function of PON1 is to protect the low-density lipoprotein cholesterol (LDL-c) and the high-density lipoprotein cholesterol (HDL-c) from oxidation and thus prevent cardiovascular diseases and atherosclerosis." (PMID 33033457, 2020). "PON-1 and ARE contribute to the protective effect of HDL against atherosclerosis." (PMID 32267365, 2020). "Higher PON1 activity has been associated with reduced CV risk in patients with and without RA12,13, and PON1 overexpression decreases atherosclerosis in animal models." (PMID 33033318, 2020). "The results of our study indicate that both PON1 c.575A>G and GRS, defined as the accumulation of pro-oxidative alleles, are suggested to exert an impact on the extent of atherosclerosis in coronary arteries, independent of other conventional risk factors." (PMID 32961879, 2020). "Mechanistically, the aortae of TIC-treated animals expressed more paraoxonase-1 (PON1), an anti-atherosclerotic molecule, in the atherosclerotic intima and exhibited higher PON1 activities in the sera, suggesting a potential role of PON1 in the superior protection by TIC against atherosclerosis." (PMID 31242230, 2019). "The first coverage report governing the alliance of the PON3 gene with serum PON1 activity in systemic lupus erythematosus (SLE) and atherosclerosis risk, did not reveal any significant association with PON3 variants." (PMID 31816846, 2019). "The most significant finding of the current study is that although CLO and TIC equally inhibited platelet aggregation, TIC protected hypercholesterolemic mice against atherosclerosis more robustly than did CLO likely through the induction and increased serum activities of PON1." (PMID 31242230, 2019). "Differently from PON-1, the “in vivo” action of Lp-PLA2 is suggested to be beneficial only in some physiological and pathological settings, whereas in others (e.g., atherosclerosis) seems to be detrimental." (PMID 29317982, 2017). "Blood high-density lipoprotein (HDL) levels are inversely correlated with atherosclerosis, with this beneficial effect of HDL being partly attributed to its antioxidant properties mediated by paraoxonase 1 (PON1) or platelet-activating factor acetylhydrolase (PAF-AH)." (PMID 28212288, 2017). "Regarding the protective role of paraoxonase against atherosclerosis progression, therefore, it can be concluded that amplified ox-LDL could pave the way for atherosclerosis progression toward atheroma and CVD through PON1 inhibition." (PMID 29118945, 2017). "Our previous study indicated the negative correlation between the activity of plasma PON1 and the extent of atherosclerosis." (PMID 26410585, 2015). "The paraoxonases (PON) are a group of antioxidant enzymes, termed PON1, PON2, and PON3 that protect lipoproteins and cells from peroxidation and, as such, may be involved in protection against the atherosclerosis process." (PMID 25993297, 2015). "There is a significant body of evidence to support a role for PON1 in atherosclerosis, and in particular against oxidation, not least its capacity to hydrolyze lipid hydroperoxides." (PMID 26528181, 2015).
atherosclerosis (continued). "Paraoxonase 1 (PON1), another member of the paraoxonase gene family that protects against atherosclerosis development, is not expressed in macrophages, and it is present in the circulation associated with HDL." (PMID 26779262, 2015). "After the introduction of the oxidative stress hypothesis of atherosclerosis and the discovery of antioxidant effect of HDL-C, PON1 attracted significant interest as a protein that is responsible for the most of antioxidant properties of HDL-C." (PMID 24222847, 2013). "Although this finding is not universal, low PON1 is a general feature of people who develop atherosclerosis." (PMID 24222847, 2013). "Nor was there any correlation between PON1 activity and CPT-MBF, suggesting that PON1 is not involved in atherosclerosis by an impairment of endothelium-dependent coronary vasoreactivity." (PMID 22214423, 2011). "It seems reasonable to assume thatthe decreased PON1 activity found among lead workers also represents areduced protection against LDL oxidation, thereby increasing the accumulationof lipid peroxides and, eventually, promoting atherosclerosis." (PMID 16882531, 2006). "These include reduced activity of paraoxonase 1 and glutathione peroxidase, which lead to increased oxidative stress and promote the formation of oxidized LDL cholesterol, both of which are critical in the pathogenesis of atherosclerosis and accelerated vascular ageing." (PMID 41226967, 2025). "Furthermore, the present study demonstrated a significant positive correlation between plasma LCAT and PON-1, suggesting that the two lipoprotein-associated enzymes may play synergistic roles on HDL particles to counter the effects of atherosclerosis and ASCVD progression." (PMID 39114750, 2024). "HDL, owing to their antioxidant activity attributed by enzymes such as paraoxonase 1 (PON-1), lecithin-cholesterol acyltransferase (LACT), and platelet-activating factor acetyl hydrolase (PAF-AH), inhibit and prevent the LDL oxidation and the consequent impact on atherosclerosis." (PMID 38248328, 2024). "Although Pon1 depletion in mice in the absence of hyperlipidemia does not induce atherosclerosis, Pon1−/− mice fed with a standard normolipidemic chow diet show an altered expression of proteins involved in vascular inflammation, oxidative stress, and thrombogenicity." (PMID 39594433, 2024). "Studies on mice showed higher levels of the aortic adhesion molecules P-selectin and ICAM1 mRNA, greater leukocyte adhesion, and higher levels of aortic superoxide, supporting the idea that a lack of PON1 means oxidative stress and the beginning of atherosclerosis." (PMID 38474211, 2024). "Some research works, but not all, have shown that in the RR genotype carriers, PON1 enzyme activities decreases, which increases oxidative stress and inflammation, and all these events may be related to the incidence of atherosclerosis and CAD." (PMID 36741829, 2022). "One proposed mechanism by which these berries attenuated atherosclerosis is increased antioxidant capacity by the upregulation of glutathione reductase (GSR) and Trx 1 (blueberry), SOD1 and SOD2 (blueberry and hawthorn berry), and GPx1 and paraoxonase-1 (PON1) (acai berry)." (PMID 32664664, 2020). "In addition to its protective effect in macrophages, PON-1 has been reported to hydrolyze short-chain oxidized PLs on LDL, thereby protecting against oxidized LDL (oxLDL) and atherosclerosis, as shown in mouse models both lacking and overexpressing serum PON." (PMID 29986413, 2018). "Therefore, upregulation of PON1 levels by non-genetic factors can have a potential advantage in such cases for better and achievable protection against atherosclerosis." (PMID 30044465, 2018). "However, although the current knowledge of PON1 provides valuable insights on the function and role of PON1, yet the role of this enzyme involved in the progression of atherosclerosis toward ‘atheroma’ is still not well investigated." (PMID 29118945, 2017).